CLINT1 (clathrin interactor 1)
Description:
Binds to membranes enriched in phosphatidylinositol 4,5-bisphosphate (PtdIns(4,5)P2). May have a role in transport via clathrin-coated vesicles from the trans-Golgi network to endosomes. Stimulates clathrin assembly.
Synonyms: Clint; ENTH; EPN4; EPNR; KIAA0171
Tractability: Antibody: UniProt places it where antibodies can reach, with medium confidence; its Gene Ontology location is reachable by antibodies, with medium confidence. PROTAC: ubiquitination databases record sites on it; its protein half-life has been measured.
Gene: Protein-coding gene on chromosome 5 (157,785,743 to 157,859,169, reverse strand). Ensembl gene ENSG00000113282.
Subcellular location: Cytoplasm; Cytoplasm, perinuclear region; Membrane; Cytoplasmic vesicle, clathrin- coated vesicle
Subcellular location (Human Protein Atlas): Vesicles; Nucleoplasm
Pathways (Reactome):
Disease: Assembly and Release of Dengue Virus Virions
Vesicle-mediated transport: Golgi Associated Vesicle Biogenesis
Gene Ontology:
Molecular function: cadherin binding; clathrin binding; protein binding; phospholipid binding
Biological process: endocytosis; clathrin coat assembly
Cellular component: Golgi apparatus; membrane; clathrin vesicle coat; cytosol; clathrin-coated vesicle; cytoplasm; endomembrane system; perinuclear region of cytoplasm
Genetic constraint (gnomAD): Loss-of-function variants: 13 observed, 49.33 expected, observed/expected ratio (o/e) 0.26, 90% interval 0.17 to 0.42. The upper end of that interval is the gene's LOEUF score, 0.42, which puts it in group 1 of 6, group 1 being the genes least tolerant of losing a copy. Missense variants: 572 observed, 714.56 expected, observed/expected ratio (o/e) 0.8, 90% interval 0.75 to 0.86. Synonymous variants: 204 observed, 234.79 expected, observed/expected ratio (o/e) 0.87, 90% interval 0.77 to 0.98.
Homologues: Orthologues: chimpanzee CLINT1 (99% identical), macaque CLINT1 (99% identical), dog CLINT1 (97% identical), rabbit CLINT1 (97% identical), guinea pig CLINT1 (96% identical), pig CLINT1 (95% identical), mouse Clint1 (94% identical), rat Clint1 (94% identical), tropical clawed frog clint1 (68% identical), zebrafish clint1a (62% identical), zebrafish clint1b (54% identical), Drosophila melanogaster lqfR (42% identical). Paralogues in human: EPN2 (24% identical), EPN3 (24% identical), EPN1 (22% identical), ENTHD1 (17% identical), MYCBPAP (13% identical).
Diseases named in the same sentence as CLINT1 in open-access papers:
CLINT1 is named in the same sentence as 14 diseases in open-access papers, as found by Europe PMC text mining. Sharing a sentence is not in itself a finding about the gene and the disease. The quoted sentences say what the papers report.
schizophrenia (2 papers, 2010 to 2012). A major psychotic disorder characterized by abnormalities in the perception or expression of reality. "This is explicitly demonstrated by the co-expression of CLINT1 associated with schizophrenia with all its interactors in the brain region associated with the pathophysiology of the disease (Brodmann area 10: anterior prefrontal cortex)." (PMID 20525321, 2010).
breast carcinoma (1 paper, 2023). "In a different cell type, BT20 breast cancer cells, knockdown of Rab4a, Rab4b, Rab11a, Rab11b or Rab25 significantly decreased motility, as did knockdown of CLINT1 or SH3BP5L." (PMID 37232246, 2023).
Chlamydia infection (1 paper, 2019). "The remaining 6 proteins identified by all 3 MS approaches–ASPH, LRRF1, LRC59, TMOD3, CLINT1, and BAP31–represent priority targets for further study in the context of Chlamydia infection." (PMID 30943267, 2019).
colon cancer (1 paper, 2019). "It was found that high expressions of NUDT21 (HR= 0.57, P = 0.023), GNB1 (HR=0.028, P=0.026), and CLINT1 (HR=0.6, P=0.043) were associated with better overall survival for colon cancer patients." (PMID 30881993, 2019). "Finally, NUDT21, COL1A2, GNB1, and CLINT1 closely related to the overall survival of colon cancer were selected as core genes." (PMID 30881993, 2019). "Moreover, further deeply investigated molecular mechanism of NUDT21, COL1A2, GNB1, CLINT1, and colon cancer is necessary; it is also the limitation of this study." (PMID 30881993, 2019). "Taken together, NUDT21, GNB1, CLINT1, and COL1A2 were considered as core genes with a close relationship to colon cancer." (PMID 30881993, 2019). "Finally, NUDT21, GNB1, CLINT1, and COL1A2 core gene were selected due to their correlation with the prognosis of IIA stage colon cancer." (PMID 30881993, 2019). "In conclusion, this study showed that NUDT21, GNB1, CLINT1, and COL1A2 might be the potential core genes that play an important role in the development and prognosis in IIA stage colon cancer." (PMID 30881993, 2019). "this study suggested that NUDT21, GNB1, CLINT1, and COL1A2 might be the core genes for colon cancer that play an important role in the development and prognosis of IIA stage colon cancer." (PMID 30881993, 2019). "And we found that NUDT21, GNB1, CLINT1, and COL1A2 might be the potential core genes that play an important role in the development and prognosis in IIA stage colon cancer." (PMID 30881993, 2019).
metastatic prostate carcinoma (1 paper, 2013). A carcinoma that arises from the prostate gland and has spread to other anatomic sites. "In addtion, the identified interactions in metastatic prostate cancer contain several experimentally confirmed targets of hsa-miR-143 and −145, including CLINT1, CDKN1A, IRS1, MAPK7, PPM1D and SOD2." (PMID 23782521, 2013).
psoriasis (1 paper, 2019). An autoimmune condition characterized by red, well-delineated plaques with silvery scales that are usually on the extensor surfaces and scalp. "Clint1 mutant zebrafish have a phenotype mimicking psoriasis, suggesting it may function in mediating inflammation." (PMID 30911049, 2019).
neurodegenerative disease (1 paper, 2015). A disorder of the central nervous system characterized by gradual and progressive loss of neural tissue and neurologic function. "We selected HSPA8, CLINT1 and SGTA as candidate proteins that could potentially be recruited into pathological aggregates in neurodegenerative disease." (PMID 26317359, 2015).
psychiatric disorder (1 paper, 2022). A disorder characterized by behavioral and/or psychological abnormalities, often accompanied by physical symptoms. "Moreover, we reveal a requirement for CLINT1 in a disease state, in which it was not previously implicated, beyond psychiatric disorders." (PMID 35452674, 2022).
CLINT1 also shares sentences with these, for which no sentence is quoted: bladder cancer (1 paper); Cerebral ischemia (1); dengue virus infection (1); lipoma (1); neuroblastoma (1); viral infection (1).